IL33 (interleukin 33)
Diseases named in the same sentence as IL33 in open-access papers (continued):
Sharing a sentence is not in itself a finding about the gene and the disease.
Hepatic steatosis (10 papers, 2016 to 2025). Steatosis is a term used to denote lipid accumulation within hepatocytes. "In this work, ST2 deficiency abolished the effects of IL-33 treatment on hepatic steatosis and fibrosis, so we might also conclude that the function of IL-33 in NASH mice was dependent on ST2 signaling." (PMID 27172901, 2016). "IL-33 can attenuate hepatic steatosis and act as an alarmin by quickly triggering the immune system to respond to virus invasion and toxicant-induced damage, thus leading to a protective effect on viral hepatitis and Con A-induced liver injury." (PMID 29180837, 2017). "In this work, treatment with IL-33 also attenuated hepatic steatosis and reduced ALT levels in mice fed with MCD diet, indicating that the function of IL-33 was not totally dependent on its modulation in glucose metabolism." (PMID 27172901, 2016). "Treatment with IL33 attenuated diet-induced hepatic steatosis, and this effect may be due to the promotional effect of IL33 on Th2 response and M2 macrophage activation in mice exposed to a high-fat diet or an MCD diet." (PMID 39000005, 2024). "We also reported how feeding SPI reduces the expression of inflammation-related genes, such as IL-33 and IL-1B, that could be helping in the general reduction of liver steatosis observed with the SPI diet." (PMID 34262928, 2021). "Because of the regulatory role played by IL-33 in lipid metabolism, IL-33 may have a close relationship with fatty liver." (PMID 29180837, 2017). "Because the IL-33/ST2 axis may have a disputably beneficial effect on fatty liver, more studies are needed to clarify its mechanism and determine its therapeutic value." (PMID 29180837, 2017). "Therefore, the modulation of IL-33 on these genes might contribute to the beneficial effect of IL-33 against hepatic steatosis in mice fed with MCD or HFD." (PMID 27172901, 2016). "Studies regarding the role of IL-33 in fatty liver disease have primarily focused on nonalcoholic fatty liver disease (NAFLD)." (PMID 29180837, 2017). "IL‐33 did not affect hepatic steatosis and fibrosis in a ST2−/− NAFLD mice model." (PMID 30478965, 2019). "IL-33 did not affect diet-induced hepatic steatosis and fibrosis in ST2 knockout mice." (PMID 27172901, 2016).
intestinal tumors (10 papers, 2016 to 2022). "We show here that expression of IL-33 is increased within epithelial cells of intestinal tumors in humans and mice and that constitutive expression of IL-33 in the context of the Apc mutation leads to increased tumorigenesis." (PMID 28710436, 2017). "IL-33 stimulation of subepithelial myofibroblasts induced the expression of extracellular matrix components and growth factors associated with intestinal tumor progression." (PMID 27148488, 2016). "Similarly, ApcMin/+ mice on an Il33-deficient background developed fewer and smaller intestinal tumors." (PMID 27148488, 2016). "Yet, additional studies are warranted to definitively address the function of IL-33/ST2 signaling for CD4+ T cell plasticity in the intestinal tumor environment." (PMID 31165767, 2019). "In other studies, the role of epithelial IL-33 in intestinal tumor development was examined in ApcMin/+ mice transgenically expressing IL-33 in intestinal epithelial cells (V33 ApcMin/+)." (PMID 30205617, 2018). "IL-33 expression was found to be increased in epithelial cells of both murine and human intestinal tumors, and IL-33 promoted tumor development in ApcMin/+ mice." (PMID 29922293, 2018). "Here we report that IL-33 is expressed by epithelial cells within human and mouse intestinal tumors." (PMID 28710436, 2017). "Here, we investigated the role of epithelial expressed IL-33 during development of intestinal tumors." (PMID 28710436, 2017). "Together, these results document expression of IL-33 in intestinal tumors of humans and mice and suggest that IL-33 is involved in their development." (PMID 28710436, 2017). "Accordingly, we found that IL-33-deficiency led to reduced intestinal tumor Tregs and mast cells, while not affecting ILC2 frequency." (PMID 35658010, 2022). "We also investigated the potential roles of IL-33 in regulating intestinal tumor ILC2s." (PMID 35658010, 2022). "While IL-25-deficiency led to a decrease in both intestinal tumor number and size, IL-33-deficiency in our study only reduced tumor number and not tumor size, in keeping with them mediating separate pro-tumorigenic pathways." (PMID 35658010, 2022). "Moreover, data have shown that MSCs adjacent to intestinal tumors express IL1RL1 and interleukin 33, which can induce activation of tumor-promoting MSCs." (PMID 34971821, 2022). "We found that intestinal tumor ILC2s had increased expression of IL-25R, but did not express ST2, and while the pro-tumoral effects of IL-25 required ILC2s, IL-33 acted independently of ILC2s correlating instead with mast cell and Treg expansion." (PMID 35658010, 2022).
metastatic tumors (10 papers, 2016 to 2025). "The fact that T cells also require antigen stimulation to up-regulate expression of CD8 implies that IL-33 induction or over-expression can overcome MHC-I deficiency of metastatic tumours in vivo." (PMID 27619158, 2016). "Overall our data shows that the reduced IL-33 expression in tumours is associated with progression to metastatic disease." (PMID 27619158, 2016). "Collectively, these data show that the reduced IL-33 expression is associated with progression to metastatic disease and reduced time to disease recurrence in patients who had resected metastatic human carcinomas." (PMID 27619158, 2016). "Overall this data suggests that reduced IL-33 expression in prostate cancer cells is associated with progression to metastatic disease." (PMID 27619158, 2016). "We find that down-modulation of IL-33 and MHC-I/HLA related genes are associated with progression to metastatic disease and discover that IL-33 downregulation is a biomarker associated with recurrence in human metastatic prostate and kidney renal clear cell carcinomas." (PMID 27619158, 2016). "IL-33 expression was elevated in muscular and serosal invasion but decreased in poorly differentiated and metastatic tumors, suggesting a dual role—potentially protective in early stages and tumor-promoting in advanced disease." (PMID 40725273, 2025). "This information will contribute to the clinical application of IL33 blockade combined with immunotherapy for the treatment of metastatic diseases." (PMID 41214328, 2025). "The difference in IL-33 expression between primary and metastatic tumors enabled examination of the involvement of ILC2s and IL-33 in cancer progression." (PMID 38524132, 2024). "We quantitatively analyzed RNA-expression from the tumour cells and identified distinct gene expression signatures in the different samples: A9 (metastatic tumours), A9+IL-33 (metastatic), and TC1 (primary tumours)." (PMID 29440650, 2018). "In particular, baseline IL-33 levels were found to be an independent prognostic factor in a subgroup of patients who received active treatment for locally-advanced or metastatic disease." (PMID 30205617, 2018). "We have demonstrated that IL-33 restores immune-responsiveness against metastatic tumours via induction of antigen processing pathways." (PMID 27619158, 2016). "Third, the re-introduction of IL-33 into metastatic tumours induces a reduction of circulating tumour cells and boosts immune recognition against metastatic tumours in vivo." (PMID 27619158, 2016). "Finally, introduction of IL-33 into metastatic tumors reduced the levels of circulating tumor cells and boosted immune recognition against metastatic tumors in vivo." (PMID 31231372, 2019). "We did not detect ILC2 cells in IL-33-deficient metastatic tumours (A9) established in either the mice transplanted with WT BM or RORα−/− BM." (PMID 29440650, 2018). "Thus, IL-33 over expression in metastatic tumors may serve as a marker of an anti-tumor response against it." (PMID 30205617, 2018).
myocarditis (10 papers, 2012 to 2026). Myocarditis is a condition that is characterized by inflammation of the heart muscle (myocardium). "Here, we investigatedthe role of the IL-33/ST2 axis in the developmentof myocarditis during acute and chronic T. cruzi infection." (PMID 41365681, 2026). "We previously showed that treatment of male mice with recombinant IL-33 during initiation of myocarditis significantly increased perimyocarditis resulting in eosinophilic myocarditis." (PMID 36741845, 2022). "ILC2 expansion and fibroblast-derived IL-33 production were significantly increased in the heart in mouse models of infarction and myocarditis." (PMID 30984196, 2019). "Our findings suggest that the combination of high viral replication and elevated IL-33 levels in the heart is likely to be important in the progression from acute CVB3 myocarditis to severe DCM and HF." (PMID 22013485, 2012). "Treatment of WT mice with recombinant (r)IL-33 increased CVB3 myocarditis and impaired cardiac function." (PMID 22013485, 2012). "Furthermore, IL-33 reporter mice showed a massive increase in IL-33 production by Sca-1+ cardiac fibroblasts during ischemia and myocarditis, which was correlated with an expansion of the ILC2 compartment." (PMID 30984196, 2019). "Thus, in the context of a Th2-driven IL-4 response elevated IL-33 protects the heart from cardiac dysfunction during acute CVB3 myocarditis." (PMID 22013485, 2012). "We show in this study that high viral replication does not itself account for increased IL-33 levels in the heart during CVB3 myocarditis because similar amounts of viral replication occurred in TLR3- and TRIF-deficient hearts, but IL-33 levels were only increased in TRIF-deficient mice." (PMID 22013485, 2012). "Th2 cell-associated cytokine IL-33 could alleviate the severity of viral myocarditis in TLR3 knock-out mice, increase the percentage of Th2 cells, and prevent the progression from acute myocarditis to chronic myocarditis." (PMID 30176160, 2018). "Because IL-33-treatment was found to decrease cardiac function during acute CVB3 myocarditis in WT mice, we tested whether rIL-33 treatment of TLR3-deficient mice (that have a classic Th2 response) could worsen myocarditis." (PMID 22013485, 2012). "Our data demonstrated that miR-487b ameliorates cell apoptosis, inflammatory reaction of myocarditis, and fibrosis through inhibiting the IL-33/ST2 pathway by suppressing IL-33, providing a novel therapy for CHF." (PMID 28881679, 2017). "In our model, we also observed increased number of eosinophils in the heart after IL-33 treatment, whereas we did not observe clinical or histological phenotypes of myocarditis according to echocardiography and histological assessments." (PMID 33456562, 2021). "Although the mechanism has not yet been elucidated, the difference in cardiac function and survival/HF between TLR3- and TRIF-deficient mice suggests that TLR4-mediated TRIF may be responsible for reducing the negative cardiac effects of IL-33 in the heart during acute CVB3 myocarditis." (PMID 22013485, 2012).
psoriatic arthritis (10 papers, 2018 to 2024). Joint inflammation associated with psoriasis. "More recently, a study of patients with psoriatic arthritis found an association between the presence of carotid plaque and total vertebral BMD and suggested a link between interleukin-33 and its decoy receptor, soluble ST2, as a pathophysiologic mediator." (PMID 34641970, 2021). "Finally, the study involving RANKL, a potent activator of bone reabsorption which is increased via IL-33, suggests a link between psoriatic cutaneous inflammation and the pathogenesis of psoriatic arthritis (PsA), thus explaining why, in most cases, Pso anticipates several decays the onset of PsA." (PMID 34944487, 2021).
Sjögren’s syndrome (10 papers, 2013 to 2023). "On other hand, Th2-associated cytokines are only important in the case of dry eye disease (IL4, IL5, IL33) and Sjögren’s syndrome (IL33)." (PMID 31810226, 2019). "Here, we assessed the expression of IL-33 and related molecules in the salivary glands (SGs) of patients with IgG4-RD versus that in patients with Sjögren’s syndrome (SS) and controls." (PMID 28205524, 2017). "Furthermore, ST2 and IL-33 were highly expressed around ectopic germinal centers in salivary glands from patients with IgG4-related disease, whereas IL-33 was expressed only in epithelial cells in patients with Sjögren's syndrome and controls." (PMID 30498500, 2018). "Although serum IL-33 levels and EULAR Sjögren's syndrome disease activity index (ESSDAI) or lymphocyte infiltration were not correlated, serum sST2 levels were significantly correlated with ESSDAI, disease duration, and thrombocytopenia." (PMID 34589505, 2021). "The IL-33/ST2 axis promotes the development of primary Sjogren’s syndrome by activating salivary epithelial cells and the type 1 immune response in a mouse model of experimental Sjogren’s syndrome." (PMID 36291105, 2022).
age-related macular degeneration (9 papers, 2019 to 2025). Age-related loss of vision in the central portion of the retina (macula), secondary to retinal degeneration. "Studies have also implicated the role of IL-33 in various ocular diseases, including glaucoma, age-related macular degeneration, and diabetic retinopathy." (PMID 40512033, 2025). "Conversely, it has been shown that the release of IL-33 from Müller cells contributes to the pathogenesis of age-related macular degeneration (AMD) by triggering an inflammatory response and photoreceptor degeneration." (PMID 37671525, 2023). "The significance of IL-33 in senescence is emphasized by the observation that IL-33 expression at both mRNA and protein level increases in age-related macular degeneration." (PMID 35093936, 2022). "In contrast to studies showing IL-33-mediated protection against retinal pathology, Xi and colleagues have reported that IL-33-expressing-Müller cells can promote inflammation and contribute to the pathogenesis of age-related macular degeneration." (PMID 31796062, 2019). "However, Xi and colleagues have found that IL-33+ Müller cells can promote retinal inflammation in retinal injury and during age-related macular degeneration." (PMID 31796062, 2019). "The current studies concerning the roles of IL-33/ST2 axis in vitreoretinal diseases mainly focused on ocular toxoplasmosis (OT) and age-related macular degeneration (AMD)." (PMID 32908451, 2020).
chronic pancreatitis (9 papers, 2018 to 2025). A chronic inflammatory process causing damage and fibrosis of the pancreatic parenchyma. "Therefore, IL-33 is considered to be a novel factor implicated in the pathogenesis of acute and chronic pancreatitis and potentially in tissue fibrosis." (PMID 30405626, 2018). "To investigate the effect of tropisetron on chronic inflammation and IL-33 signaling in vivo, we induced chronic pancreatitis in WT mice by IP injection of caerulein, administered hourly for 6 h each day, three days per week, over a three-week period." (PMID 40647388, 2025). "Accordingly, pitavastatin prevents chronic pancreatitis and its cancer sequela in an IL-33-dependent manner." (PMID 38816352, 2024). "Accordingly, pitavastatin prevented chronic pancreatitis and its cancer sequela in an IL-33-dependent manner." (PMID 36711701, 2023). "Serum IFN-α and IL-33 concentrations in patients who met the diagnostic criteria for definite type 1 AIP and/or IgG4-RD were significantly higher than in those with chronic pancreatitis or in healthy controls." (PMID 32938972, 2020). "Although several lines of evidence demonstrate a role for IL33 in fibrogenesis during chronic pancreatitis, investigations into the potential function of IL33 in the pathogenesis of AP are limited." (PMID 32751171, 2020). "To investigate whether the therapeutic effects of tropisetron were mediated through IL-33 suppression, we subjected Il33KO mice to caerulein-induced chronic pancreatitis protocol along with tropisetron versus PBS treatment." (PMID 40647388, 2025). "Additionally, IL-33 is a novel factor involved in the pathogenesis of chronic pancreatitis and possibly pancreatic cancer." (PMID 30405626, 2018). "IL-33 signaling has also been involved in the pathogenesis of acute and chronic pancreatitis." (PMID 30405626, 2018). "Accordingly, increased IL-33 and interferon-α, produced by dendritic cells, are reported in patients with definite type 1 AIP compared with chronic pancreatitis or healthy controls." (PMID 35884816, 2022). "The usefulness of IFN-α and IL-33 as biomarkers for AIP/IgG4 was evaluated in 21 patients with AIP/IgG4, 12 patients with chronic pancreatitis, and 8 healthy subjects." (PMID 33923064, 2021).
inflammatory skin disease (9 papers, 2015 to 2025). Inflammatory skin disorders covers a broad category that includes many conditions ranging in severity, from mild itching to grave medical health complications These disorders are common in people of all ages and races. "As a bifunctional factor, IL-33 plays a physiological role as a nuclear protein and an endogenous risk signal to exert inflammatory effects in numerous inflammatory skin diseases." (PMID 34925005, 2021). "Recent studies have suggested that IL-33 and IL-37 are new potential therapeutic targets in inflammatory skin diseases." (PMID 37834081, 2023). "The role of IL-33/IL-37 interactions in inflammatory skin diseases has been reported." (PMID 37834081, 2023).
ischemia (9 papers, 2014 to 2024). A hypoperfusion of the BLOOD through an organ or tissue caused by a PATHOLOGIC CONSTRICTION or obstruction of its BLOOD VESSELS, or an absence of BLOOD CIRCULATION. "Recently, it has been proposed that smoking, the main risk factor of the disease, could induce IL-33-mediated immune responses that would result in vascular endothelial damage with subsequent thrombosis and ischemia." (PMID 29848379, 2018). "Endogenous IL-33 has also been identified as a disease-driving factor in liver ischemia/reperfusion (I/R) injury, another disease with hepatic lesions." (PMID 38571949, 2024). "Another recent study found that IL-33/growth stimulation expressed gene 2 (ST2) signaling activated beneficial M2 macrophage polarization after ischemia and subsequently reduced neuronal cell death." (PMID 29540209, 2018). "Our research shows that IL-33/ST2 protein levels are elevated after ischemia, accompanied by astrocyte and microglia activation, and this trend was reduced by both iPSC-EVs and EA treatment, whereas a more significant decrease in these levels was observed in the EA+iPSC-EVs group." (PMID 35269441, 2022). "We investigated whether IL33-MSCs influenced macrophage polarization, which has an important effect on the immunoregulation of the early stage of ischemia-reperfusion injury." (PMID 31547872, 2019). "Similarly, rat IL-33 axis is also increased after ischemia, and a further increase induced by celastrol induces M2 microglia phenotype." (PMID 29540209, 2018). "In the same line of evidence, acquired even before IL-33 was identified as ST2 ligand, administration of sST2-Fc fusion protein in mice was shown to attenuate inflammation in intestinal ischemia reperfusion, in support of the alarmin function of IL-33 during IRI." (PMID 24586382, 2014). "Celastrol stimulates IL-33 expression and activates the IL-33/ST2 pathway after ischemia by inducing beneficial M2 polarization of microglia/macrophages, thereby suppressing ischemia-induced inflammatory factors expression." (PMID 37458258, 2023).